INS (insulin)
Diseases named in the same sentence as INS in open-access papers (continued):
Sharing a sentence is not in itself a finding about the gene and the disease.
Insulin resistance (continued). "Pathogenesis of both diseases can be considered a continuum of dysglycemia with development of impaired insulin secretion and insulin resistance as common pathogenic link." (PMID 29348892, 2017). "In metabolic disorders on the contrary, adipocytes become larger in size, inflamed, insulin resistant, and increasingly express harmful adipokines leading to adipose tissue dysfunction, insulin resistance and associated diseases." (PMID 28972997, 2017). "Consistently, we present herein that increased hepatic Fas expression induced both ceramide and DAG formation, which was associated with perturbed insulin signaling and increased hepatic insulin resistance." (PMID 28883393, 2017). "The IRS1 protein is critical for insulin response, and impairment of insulin signaling by IRS1 is linked to insulin resistance." (PMID 28117714, 2017). "There is a direct association between HbA1c and insulin resistance, where HbA1c has been shown to be more strongly associated with the insulin sensitivity in healthy individuals with normal glucose tolerance." (PMID 28934974, 2017). "The present study filled the knowledge gap, and revealed that dietary Se intake is indeed associated with low insulin resistance suggesting a beneficial effect of dietary Se on insulin sensitivity." (PMID 28380029, 2017). "As regards insulin, it is well known that the high circulating ghrelin level is associated with lower insulin resistance in the general population and exogenously infused ghrelin reduces insulin secretion in healthy humans." (PMID 28596789, 2017). "WD-associated microbiota alterations impair peripheral insulin sensitivity, which is strongly linked with central insulin resistance and hippocampal dysfunction." (PMID 28194099, 2017). "A causal association is suggested by the observation that peripheral insulin resistance can be modulated by changes in central insulin signaling tone in humans." (PMID 29228027, 2017). "Together these results show the important role of AT distribution in insulin resistance and that AT sensitivity to insulin is linked to its localization." (PMID 28894286, 2017). "Taken together, these results suggest that leptin, insulin, and insulin resistance are associated with cholelithiasis." (PMID 29088261, 2017). "Several pathological conditions, such as insulin resistance and insulin gene mutations, increase ER stress in pancreatic β-cells, which leads to hyperglycemia." (PMID 28208663, 2017). "An inverse association of fasting insulin with periosteal circumference has been reported in healthy adolescents, and insulin resistance correlated inversely with periosteal and endosteal circumference." (PMID 29133833, 2017). "Increased tissue lipid levels and hepatic insulin resistance are linked through toxic lipid metabolites (diacylglycerol and ceramide species) that alter insulin signaling." (PMID 29340108, 2017). "Indinavir has been shown to inhibit insulin-stimulated glucose uptake into adipocytes in an animal model and caused insulin resistance after 4 weeks of exposure in healthy subjects." (PMID 28293638, 2017). "Earlier studies showed a positive association of insulin and insulin resistance with fat mass in childhood and adulthood." (PMID 27170102, 2017). "While hepatic insulin resistance is strongly associated with fat and muscle insulin resistance, elevated insulin secretion in the fasting state is a late marker of beta cell dysfunction." (PMID 28409212, 2017). "In humans, a meta-analysis demonstrated an association between angiogenesis and insulin sensitivity, showing that a chronic insufficiency in tissue vascularization contributes to insulin resistance." (PMID 28355132, 2017). "A state of insulin resistance, which includes a high level of circulating insulin, has been associated with a higher risk of melanoma incidence." (PMID 28223541, 2017).
Insulin resistance (continued). "LAP, composed by WC and TG, used as an indicator of insulin resistance, has already been associated with increased BMI, fasting glucose and fasting insulin in PCOS." (PMID 28784626, 2017). "McLaughin reported a positive association between visceral AT and insulin resistance, and between subcutaneous AT and insulin sensitivity, after BMI adjustment." (PMID 28894286, 2017). "Several other studies in humans as well as dogs have supported the findings that defective hepatic insulin clearance is implicated in diet-induced insulin resistance." (PMID 28184213, 2017). "In a recent study, endothelial Fcγ receptor IIB activation was shown to blunt insulin delivery to skeletal muscle, causing insulin resistance in mice." (PMID 28848738, 2017). "The levels of insulin, ultrasensitive C-reactive protein and uric acid were also associated with insulin resistance." (PMID 28492722, 2017). "Since elevated hepatic NEFA can cause liver insulin resistance, it is conceivable that improved lipid metabolism in the obese mice that contributed to improved insulin sensitivity and glucose metabolism in the obese mice." (PMID 28555111, 2017). "In a study on rats with induced T1DM, it was demonstrated that secondary insulin resistance developed immediately after deprivation of insulin reserve and that this was associated with fetuin-A levels." (PMID 28529199, 2017). "Both cell culture and animal studies have shown TNF-alpha to interfere with the insulin pathway causing insulin resistance." (PMID 29209160, 2017). "The hypertension is frequently associated with insulin resistance, and insulin can modify the functional activity of the hypothalamus, supporting the findings concerning the different metabolism of SHR rats compared to the normotensive animals." (PMID 28638832, 2017). "The homeostatic model assessment–insulin resistance (HOMA-IR) reflecting high blood levels of insulin and glucose is positively associated with breast cancer in the postmenopausal women." (PMID 28446149, 2017). "Hypertrophic obesity is usually associated with insulin resistance, and the hyperplasic type with insulin sensitivity." (PMID 28837146, 2017). "Obesity-associated insulin resistance, characterized by intracellular defects in insulin action, is central to the etiology of related metabolic disturbances." (PMID 28099843, 2017). "In non-diabetic populations – especially among youth – increased insulin secretion precedes insulin resistance and, in the presence of obesity, indicates a risk of developing type-2 diabetes." (PMID 28286536, 2017). "Glucose and insulin metabolism in our group showed an increased risk for developing insulin resistance; however, HbA1c levels were normal in all our patients." (PMID 28278160, 2017). "Chronic plasmatic cortisol elevation has been associated with insulin resistance, independently of obesity through a mechanism that would impair β-pancreatic function and peripheral tissue insulin sensitivity." (PMID 28542472, 2017). "Low-grade systemic inflammation is often associated with insulin resistance and impaired insulin secretion, the two key mechanisms underlying the pathophysiology of type 2 diabetes." (PMID 28911155, 2017). "Along with our findings, evidence has been reported for an association of the ADAMTS9 gene with insulin sensitivity, insulin resistance, and T2D." (PMID 28225792, 2017). "Insulin resistance was positively associated with insulin concentration (.922**) and FBG (.714**) in the women with GDM." (PMID 28732072, 2017). "The current study further supports the notion that GHS- R ablation and ghrelin ablation exert differential effects on sugar-induced insulin resistance: ghrelin deficiency worsens insulin sensitivity whereas GHS-R deficiency improves insulin sensitivity." (PMID 28629187, 2017).
Insulin resistance (continued). "The major cause of insulin resistance in childhood is a typical lipid partitioning pattern characterized by increased deposition of lipids within insulin responsive tissues, such as the liver and skeletal muscle and within the viscera." (PMID 29280741, 2017). "For example, it was generally believed that the obesity and insulin resistance stress conditions associated with T2D led to islet β-cell failure cell death and reduced insulin+ cell mass." (PMID 28424732, 2017). "In healthy postmenopausal women, leg fat mass was a significant independent predictor of insulin sensitivity, reducing risk for hyperinsulinemia and insulin resistance, whereas trunk fat was associated with increased risk of those conditions." (PMID 28441953, 2017). "While adiponectin-deficient mice developed hepatic insulin resistance, administrating adiponectin or upregulating its plasma concentrations substantially improved insulin sensitivity in the liver and skeletal muscle of animals or humans." (PMID 28786989, 2017). "TC risk is also increased in metabolic syndrome characterized by long-standing insulin resistance, confirming the fundamental role of elevated insulin and glucose levels in the pathogenesis of this association." (PMID 29184536, 2017). "The defects in insulin signaling pathway often lead to insulin resistance, which is an important risk factor for metabolic dysfunctions and other diseases." (PMID 28835770, 2017). "Insulin resistance (IR), characterized by decreased cellular response to insulin, is among the metabolic disorders associated with OSA." (PMID 28384333, 2017). "Prolong feeding of HFD has been reported to increase the insulin level, causing insulin resistance and hyperinsulinemia in rats." (PMID 28228098, 2017). "PCOS is associated with insulin resistance which will be augmented by the hormones of pregnancy that counter the action of insulin." (PMID 28279160, 2017). "Elevation of serum triglyceride is not caused by insulin deficiency, but is often associated with a relative decrease in insulin action (i.e. insulin resistance)." (PMID 29089472, 2017). "It has been closely associated with a generalized metabolic disorder called insulin resistance, in which tissue responsiveness to the normal action of insulin is impaired." (PMID 28744376, 2017). "The first is the loss of insulin signaling, either due to insulinopenia (type 1), or insulin resistance (type 2), and secondly, is the resultant elevated blood glucose levels." (PMID 28066166, 2016). "Vascular insulin resistance is characterized by the inability of a tissue to respond to insulin and vascular insulin resistance is associated with decreased NO production." (PMID 27562094, 2016). "Adiponectin is an adipokine secreted from adipocytes to regulate insulin sensitivity, and its low circulating levels are associated with insulin resistance and type 2 DM." (PMID 27070585, 2016). "Elevated circulating irisin is associated with lower risk of insulin resistance indirectly through lowering fasting insulin." (PMID 27473122, 2016). "The pathophysiology of feline diabetes mellitus (FDM) is similar to human type 2 diabetes (T2D), including a strong association with obesity, insulin resistance and β-cell failure causing impaired insulin secretion." (PMID 27136422, 2016). "If hyperactivation of mTORC1 in insulin-sensitive tissues was the cause of insulin resistance in AdicerKO mice, one would expect this phenotype to be reversed by selective inhibition of mTORC1, as previously shown." (PMID 27241713, 2016). "Unlike obese mice on the C57BL/6 background, the Ks Leprdb/db mice are highly susceptible to β-cell failure in the setting of insulin resistance, and they develop early insulin depletion, severe hyperglycemia, ketoacidosis and early death." (PMID 27110686, 2016). "The relative deficiency of insulin secretion and varying degrees of insulin resistance is characterized by high circulating glucose levels." (PMID 27754407, 2016).
Insulin resistance (continued). "NAFLD is now the most prevalent liver disorder in the developed countries and is associated strongly with the development of hepatic insulin resistance and reduced whole-body insulin sensitivity." (PMID 28036389, 2016). "The T allele of TCF7L2 rs7903146 polymorphism was associated with a reduced compensation of insulin secretion for insulin resistance induced by 9 days of bed rest." (PMID 27058589, 2016). "Myo-inositol and its isomer D-chiro-inositol (D-chiro-Ins) participate in both insulin and glucose metabolisms, and deregulated myo-Ins metabolism has been documented in several conditions associated with diabetes or insulin resistance." (PMID 27795708, 2016). "DCI functions as second messenger in the insulin signaling pathway and it is considered an insulin sensitizer since deficiency in tissue availability of DCI were shown to cause insulin resistance (IR)." (PMID 27582109, 2016). "One of the earliest reports of such a mechanism described a rare form of insulin resistance in humans caused by InR auto-antibodies, which prevented the binding of insulin to its receptor." (PMID 27053133, 2016). "Inactivation of PPARs is associated with insulin resistance, yet paradoxically Id2−/− mice show enhanced insulin sensitivity with downregulated PPARs." (PMID 27144179, 2016). "Plasma vitamin C concentrations, in contrast, showed strong inverse associations with fasting insulin and insulin resistance, glucose and urate, and a positive association with HDL cholesterol." (PMID 26498636, 2016). "Like obesity, vitamin D deficiency has become a global epidemic and a risk factor for T2DM, which is characterized by insulin resistance and altered insulin secretion." (PMID 26799569, 2016). "Although investigations into T2DM pathophysiology commonly focus on insulin resistance, and impaired insulin secretion, recent data suggest a broader range of causes." (PMID 27437767, 2016). "Our results demonstrated that TCF7L2 rs290487, rs6585194 and rs7094463 polymorphisms were correlated with insulin resistance and insulin secretion of patients with GDM." (PMID 27465520, 2016). "Type 1 diabetes is caused by autoimmune-mediated destruction of pancreatic beta-cells, and type 2 diabetes is caused by both insulin resistance and relative deficiency of insulin." (PMID 27110066, 2016). "We conducted this study to assess the association of cotinine concentration with insulin resistance and insulin secretion function, using data from the National Health and Nutrition Examination Survey (NHANES) 2007–2012." (PMID 27992538, 2016). "This reduction in insulin clearance is initially compensated for an increase in insulin uptake by proximal tubular cells, and it is also associated with an increase in insulin resistance 45,46." (PMID 26872083, 2016). "Inflammatory signaling pathways are associated with insulin resistance and impaired glucose uptake, whereas adiponectin is an important, though controversially discussed, counterpart being positively associated with insulin sensitivity." (PMID 27069930, 2016). "The key pathogenic mechanism of DR is hyperglycemia due to impaired insulin action as the result of insulin deficiency or insulin resistance." (PMID 27802330, 2016). "Consumption of HAM-RS2 at 30 g/day in the form of a snack food item was associated with improved insulin sensitivity in women with insulin resistance." (PMID 26766961, 2016). "Our results have indicated that insulin resistance can cause a net gain in liver fat, and this can occur when tissues other than the liver were insulin resistant." (PMID 27306890, 2016). "Greater TAC was associated with higher consumption of tea and wine, which was inversely associated with insulin level, insulin resistance, LDL, TG, inflammation, and oxidative stress." (PMID 26742057, 2016). "The development of insulin resistance and type 2 diabetes (T2D) is closely associated with the abnormal regulation of insulin on carbohydrate metabolism." (PMID 26934990, 2016).
Insulin resistance (continued). "Oxidative stress would seem to be a key factor in diabetic complications, including CVD, and it is also closely associated with insulin resistance and impaired insulin secretion, resulting in the development of the disease." (PMID 28933391, 2016). "The metabolic syndrome is caused by the increase in plasma levels of insulin and glucose resulting in insulin resistance." (PMID 28228803, 2016). "Nonetheless, T2D occurs across a spectrum of insulin resistance, and GWAS candidates have been found to associate independently with either insulin sensitivity or insulin secretion." (PMID 27053133, 2016). "Together, the data suggest that blocking CCR5 receptors in hypothalamus interferes with hypothalamic insulin signaling and causes peripheral glucose intolerance and insulin resistance." (PMID 27898058, 2016). "Inhibition of PI3K or Akt results in shutting down the insulin cascade and is considered a primary cause in the development of insulin resistance." (PMID 27375480, 2016). "Our group has recently demonstrated that insulin resistance was associated with increased postprandial forearm muscle VLDL-TAG uptake in insulin resistant men." (PMID 26985905, 2016). "In particular, excessive FFA leading to lipotoxicity is a recognized risk factor for the development of insulin resistance and has been mechanistically linked to a downregulation of the insulin and PPARs signaling pathway in metabolic tissues." (PMID 26946982, 2016). "This raised the suggestion that association of the circulating levels of insulin with arterial FDG uptake is a function of insulin resistance, which was corroborated by a strong correlation between HOMA-IR and arterial wall inflammation." (PMID 27887576, 2016). "Consistent with the findings of previous studies, we observed that short sleep duration is significantly associated with metabolic abnormalities, including higher BMI, raised fasting insulin levels, and increased risk of insulin resistance." (PMID 27870902, 2016). "Our study demonstrated that by being overweight and obese, adolescent girls faced a higher risk of having a high fasting insulin and insulin resistance as compared to boys." (PMID 27824069, 2016). "The majority of people are affected by type 2 diabetes (T2D) that is caused by impaired insulin secretion and/or insulin resistance that leads to improper blood glucose metabolism." (PMID 27672665, 2016). "Intrauterine under-nutrition has been linked with an elevated risk of dyslipidemia and insulin resistance, a decrease in insulin content and hyperglycemia in female offspring." (PMID 27051525, 2016). "In an effort to identify new variants associated with insulin resistance, large-scale meta-analyses of GWAS have been performed using multiple cohorts which have measures of insulin sensitivity, processing and secretion." (PMID 27312935, 2016). "Whilst insulin resistance and the associated hyperinsulinaemia are detrimental to the liver, there are data showing that the exogenous administration of insulin to type 2 diabetic patients can be beneficial." (PMID 26856933, 2016). "Defects in insulin signal transduction lead to insulin resistance, which is the main cause of metabolic diseases." (PMID 27187341, 2016). "It was well-known that T2DM is characterized by insulin resistance and impaired insulin secretion caused by insufficiency of pancreatic beta-cells." (PMID 28066696, 2016). "Preclinical and clinical studies indicate that downregulation of this pathway is associated with insulin resistance and its upregulation is linked to enhanced insulin sensitivity." (PMID 26770984, 2016). "On the other hand, an impairment in insulin secretion capacity, a decrease in insulin sensitivity on both hepatic and peripheral tissues, and an increase in the level of insulin resistance have been associated with HD." (PMID 27627435, 2016).